CD4 (CD4 molecule)
Diseases named in the same sentence as CD4 in open-access papers (continued):
Sharing a sentence is not in itself a finding about the gene and the disease.
Obesity (continued). "Adipose tissue T cell populations changed with increasing obesity in mice, and an increase in the ratio of CD8+ to CD4+ was reported by various research groups." (PMID 29867762, 2018). "Here, we review studies of adipose tissue CD4+ and CD8+ T cell populations in HIV and SIV, and contrast the findings with those reported in obesity." (PMID 30559739, 2018). "Compared to CD4+ T cells, CD8+ T cells show a greater increase in adipose tissue in obesity and in aging." (PMID 30619305, 2018). "It has been suggested that obesity triggers major histocompatibility complex (MHC) class II expression on adipocytes and activates CD4+ T cells to initiate inflammation in adipose tissue." (PMID 30356025, 2018). "Furthermore, deficiency of T cells, including CD4+ T cells or IFN-γ significantly reduces adipose tissue inflammation and improves insulin sensitivity in obese mice, suggesting the substantial contribution of Th1 cells to adipose inflammation and metabolic dysfunctions associated with obesity." (PMID 30459770, 2018). "An enrichment of adipose tissue CD8+ T cells and an increase in the CD8:CD4 ratio accompanies HIV and SIV infection, which is a phenomenon also observed in obesity." (PMID 30559739, 2018). "Similar to CD4+ T cells, CD8+ T cells are significantly increased in adipose tissue in obesity in both humans and mice." (PMID 30459770, 2018). "Mechanically, it is suggested that, as obesity advances, leptin secreted by adipocytes stimulates IFN-γ production from CD4+ T cells, which further promotes adipocyte MHCII expression and thus Th1 differentiation, leading to a vicious cycle of AT inflammation." (PMID 30233575, 2018). "It has also been shown that obesity induces MHC class II expression on adipocytes and thus activates CD4+ T cells to initiate adipose tissue inflammation." (PMID 28251163, 2017). "In fact, CD4 and CD8 T cell numbers were positively associated with some, but not all, obesity indicators in the study subjects (data not shown), suggesting that the T-cell expansion associated with obesity may also contribute to the reduction of TREC levels to some extent." (PMID 24651652, 2014). "Both CD4+ and CD8+ T cells have been found in adipose tissue, and their number increases with obesity in both humans and mice." (PMID 24823865, 2014). "Additionally, reductions in CD4+CD45RO+, CD8+, CD8+CD28−, and CD8+CD45RO+ (% and cells/μL) have been correlated with decreased MS, further suggesting improvements in obesity-related inflammation." (PMID 41155165, 2025). "Although a lower prevalence of obesity was also observed in the LTBI group within the CD4 counts > 500, this difference was not statistically significant." (PMID 41305316, 2025). "Adipose tissue in obesity is characterized by the infiltration of interferon (INF)-γ-producing CD8+ and Th1 CD4+ T cells, which promote the secretion of pro-inflammatory cytokines by macrophages and leads to chronic, ongoing inflammation and contributes to local and systemic IR." (PMID 40136618, 2025). "Notably, obesity-induced alterations in metabolic and immune signaling pathways significantly impact the function of immune cells, particularly CD8+ and CD4+ T cells, in the development of HCC." (PMID 39000296, 2024). "While most conventional and HIV-related factors were only significantly associated with the incidence of CVD during the 5-year and 10-year follow-ups, factors including hypertension, obesity, CKD, recent CD4, and percent of years in retention in care had a long-term impact on CVD incidence." (PMID 38664682, 2024). "Some studies indicate that CD4+ Treg cells are reduced in circulation in people with obesity, while others do not." (PMID 38397455, 2024). "It is important to mention that this reduction can be attributed to the increased white blood cell count in people with obesity, rather than to an actual reduction in the number of CD4+ Tregs in the PB." (PMID 38397455, 2024).
Obesity (continued). "However, Sun and collaborators (2020) reported a reduction in the expression of TIM-3 within CD4+ and CD8+ T cells, when comparing people with obesity and people with obesity and T2D." (PMID 38397455, 2024). "In addition, obesity and the associated inflammation drive functional and phenotypic changes in T-cell populations, with elevations in CD4+ and CD8+ T-cell populations observed in obese individuals and in a mouse model of obesity." (PMID 39116149, 2024). "In addition to constituting a characteristic genus in PLWHIV in the Chinese population, it was reported in the Spanish population under virological suppression with >250 CD4+ T cells/μL, as well as in PLWHIV with obesity." (PMID 38732048, 2024). "In fact, according to multiple reports, the prevalence of overweight and obesity in newly diagnosed IBD proportionally related to the prevalence observed in general population, being about two to three times higher among UC children compared to CD4,7,8,10–12." (PMID 38042899, 2023). "Moreover, a recent study has also reported that caloric restriction delayed immune senescence and increased levels of hepatic CD4+ and CD8+ T cells in obesity-related HCC via shaping gut microbiome." (PMID 37266440, 2023). "Morbid obesity led to a shift from naïve to memory CD4+ T cells, which was not rescued by bariatric surgery within 9 – 11 months p.s." (PMID 37266430, 2023). "The high CD4 lymphocytes were probably due to obesity itself, and synbiotics were not able to downregulate them, at least during the 60 days of intervention." (PMID 37859769, 2023). "Patients with obesity-related non-atopic asthma present an increased INF signature at the RNA sequence of the CD4+ Lymphocytes." (PMID 37189844, 2023). "In the class 4 obesity group, we found positive correlations between the absolute number of CD4+CD45RO+ T lymphocytes and TBF, and a negative association between the absolute number of CD8+CD28- lymphocytes and age." (PMID 37334132, 2023). "In a partial contradiction with that, ASCs isolated from patients with obesity and T2D or nondiabetic donors with normal weight, were able to comparably increase the frequency of CD4+ CD25+ FOXP3+ even in coculture with anti-CD3/CD28- purified CD4 T cells." (PMID 37462786, 2023). "Indeed, our CD4-depletion study results showed that the number and exhaustion of CD8+ T cells in tumors were affected by both CD4-depletion and HFD-induced obesity, respectively." (PMID 36611881, 2022). "Another cohort study performed in 18 pregnant women showed that umbilical cord blood (UCB) collected from the placenta of mothers with obesity had increased lymphocyte subsets CD3+, CD4+, CD8+, NK, and CD8+CD25+Foxp3+ Treg cells while CD34+ cells, in which HSPCs are enriched, were decreased." (PMID 36189369, 2022). "To identify the dominant cellular sources responsible for the upregulation of CCL5 in eWAT by obesity, we detected the expression of CCL5 in CD4+ T cells, CD8+ T cells, macrophages, and adipose tissue stem cells (ASCs) in eWAT from lean and obese mice by flow cytometry." (PMID 36713454, 2022). "Several studies have reported significantly lower CD4+ cell gain after ART in obese patients than patients with normal body mass index, suggesting that obesity may adversely affect immune reconstitution." (PMID 36584083, 2022). "In conclusion, although absolute numbers of CD4+ and CD8+ T cells, B cells, NK cells and monocytes are increased in MOP, obesity-induced effects of the composition of the immune system are confined to a more differentiated phenotype of CD8+ T cells and B cells." (PMID 34354700, 2021). "We found that stimulation increased Ki67 expression in CD4+ T cells from obese PLWH compared to lean PLWH, suggesting that obesity may promote increased CD4+ T cell proliferation in the context of HIV infection." (PMID 35111163, 2021). "Our findings also suggest that the effect of leptin on IL-17A production in CD4+ T cells is not influenced by obesity status." (PMID 35111163, 2021).
Obesity (continued). "On the other hand, similar to our obesity study we found a significantly (p = 0.0002) lower proportion of natural killer (NK) cells (i.e., both CD56 bright and dim cells) and higher Tregs (CD4 + CD127low/-CD25 + FoxP3 + cells), suggesting a potentially poorer ability to kill cancer cells." (PMID 33173057, 2020). "Given that AHR may not be involved in Th1 polarization, it is quite possible that Th polarization in obesity and T2D may be regulated, at least partially, by expressions of AHR in other cell populations (e.g., monocyte) other than CD4+ T lymphocyte itself." (PMID 32849564, 2020). "Depletion of CD8+ T cells in WT mice protects against obesity-induced IR, and the transfer of CD4+, but not CD8+ T cells, to Rag1–/– mice improves IR, suggesting that the CD4+/CD8+ T-cell balance is crucial for AT homeostasis." (PMID 32973799, 2020). "Given that obesity did not impact the composition of peripheral blood CD4+ and CD8+ populations, we next asked if it impacted their functional capacity." (PMID 32469992, 2020). "In obesity, the proportions of these cells tend to decrease in the absence of March1 with a significant reduction observed in CD4+ T cells." (PMID 32973799, 2020). "Despite this limitation and the lack of information on pregnancy during the follow-up period, variables identified here as correlates of overweight/obesity among ART recipients, namely CD4 count, gender and DRC deserve attention so as to minimize morbidity among ART recipients." (PMID 32395339, 2020). "Adipocytes may present antigens via MHC-II molecules, which can also activate CD4 + T-cells and in turn promote ATM M1 polarization and inflammatory cytokine secretion in HFD-induced obesity." (PMID 32603641, 2020). "On the other hand, leptin mutant ob/ob mice were shown to have increased peripheral Foxp3+ CD4+ Treg cells compared to WT mice, further supporting the role of leptin, and not obesity alone, in decreasing Treg cell proportions." (PMID 33584724, 2020). "The analysis of the immune cells in the lung tissue revealed that obesity did not affect the number of total inflammatory cells, CD4+ T cells, or the Foxp3+ Tregs in the lungs." (PMID 33256137, 2020). "Notably, several studies found that HIV and SIV were accompanied by a substantial increase in the proportion of adipose CD8+ T cells relative to CD4+ T cells, which is strikingly similar to the enrichment in CD8+ T cells also described in obesity." (PMID 30941121, 2019). "With regard to adiponectin and leptin, two critical mediators of metabolic homeostasis in adipose tissue and possible regulators of CD4+ T cell function, leptin treatment increased IFN-γ+ CD4+ T cell frequencies in NCD mice and slightly reduced Th1 and Th17 frequencies during obesity." (PMID 31736971, 2019). "B cell-null mice on a HFD also had less frequent IFN-γ-producing CD4+ and CD8+ T cells and overall less IFN-γ production by VAT, suggesting additional mechanisms may impact the outcome of B-T crosstalk in obesity." (PMID 31379820, 2019). "Furthermore, GABA treatment inhibited obesity-related inflammation, reducing the frequency of VAT macrophage infiltrates and increasing the frequency of splenic CD4+Foxp3+ Tregs in high-fat diet-fed mice." (PMID 29867762, 2018). "Conventional T cells, including CD4+ Th1 cells and effector CD8+ T cells, are elevated in adipose tissue and may play important roles in adipose tissue inflammation in both aging and obesity." (PMID 30619305, 2018). "Analyses of T cell subsets showed that the frequency of T helper cells (CD4+) was not altered in obesity, and the frequency of cytotoxic T cells (CD8+) was slightly, but not significantly, reduced in the obese study group." (PMID 29560551, 2018). "During obesity, the proportion of adipose CD8+ T cells to CD4+ T cells increases." (PMID 29868016, 2018).
Obesity (continued). "The finding of a more clonal CD8+ T cell population in the adipose tissue of PLWH, and elevated CD4+ and CD8+ clonality in obesity, raises the question of where and how antigen might be presented to drive TCR clonal expansion." (PMID 30559739, 2018). "With developing obesity, CD4+Foxp3+ regulatory T cells are no longer able to counteract pro-inflammatory IFN-γ secreting CD8+ and CD4+ T cells." (PMID 28590409, 2017). "The balance between pro-inflammatory and anti-inflammatory T cells is modified during obesity-induced inflammation, the pool of pro-inflammatory T cells such as CD4+ and CD8+ T cells is increased and anti-inflammatory T cells such as Tregs are decreased in diet-induced obesity." (PMID 29088831, 2017). "Obesity induced by HFD increased the CD8+/CD4+ ratio (p = 0.020), while reducing the population of CD4+ T cells (p = 0.027) and of Foxp3+ Tregs (p = 0.001) within the CD3+ CD4+ T cell population in adipose tissue compared to the SD." (PMID 26161548, 2015). "Clinical factors strongly associated with obesity included female gender, black African ethnicity, non-smoking, age, and CD4 count (all P < 0.001); greater duration of cART did not predict obesity." (PMID 25431572, 2014). "This indicates that neither CR nor the spice compounds affect CD4+ T cell differentiation under HFD/obesity." (PMID 23531279, 2013). "We found that obesity and the anti-diabetic drugs changed the circulating lymphocyte subsets: HFD increased the numbers of CD4 T cells and B cells and Sal and Pio treatments reduced the numbers of CD4 and CD8 T and B cells, although these changes did not achieve statistical significance." (PMID 24376593, 2013). "An increase in memory T helper lymphocytes (CD4+CD45RO+) (% and cells/μL) has shown a negative association with the FFM percentage in Mexican women and men > 18 years old with different degrees of obesity." (PMID 41155165, 2025). "However, overall NKG2D expression (MFI) was not affected by obesity, likely because its upregulation was predominantly observed in CD4− iNKT cell subpopulations, but not in the CD4+ subset." (PMID 41000378, 2025). "Participants with obesity and insulin resistance, not taking medication for T2D, showed a higher percentage of CD4+CD8+ T cells within T cells (IRn: 2.8% ± 1.1; Pre-T2D: 2.2% ± 2.0) compared to T2D patients under treatment (1.6% ± 1.9, p < 0.05 for IRn vs. T2D)." (PMID 38397455, 2024). "Likewise, a reduction in PD-1+ among T17-like and T1/17-like CD4+CD8+ T cells in the OB vs. nOB group (p < 0.05), more marked in Class III obesity, IRn, and Pre-T2D for the T17-like cells (p < 0.05) and in Class IV for the T1/17-like CD4+CD8+ T cells (p < 0.05), was observed." (PMID 38397455, 2024). "In the context of obesity, dyslipidemia has been demonstrated to increase leptin and reduce adiponectin levels, triggering a pro-inflammatory immune response (IFN+/IL17+CD4+ T cells) while reducing levels of cells modulating the inflammatory response (Foxp3+CD4+ T cells)." (PMID 39685484, 2024). "In addition, blocking CD4+ and CD8+ T cell activation in mice with anti-CD40L antibody reduces weight gain, mitigates VAT inflammation, and alleviates obesity-induced IR, also supporting the role of T cell activation in the development of obesity and IR." (PMID 38455510, 2024). "In addition, obesity has been reported to alter the trafficking profiles of T-cells, where memory CD4+ T-cells from HFD-fed mice preferentially migrate to non-lymphoid (i.e. peripheral tissues) in a CXCR3-dependent manner, even in chow-fed mice." (PMID 36891817, 2023). "Thus, obesity-induced changes in CD4+, but not CD8+, T cell production of IFN-γ depends on T cell-specific leptin receptor expression." (PMID 37276236, 2023).
Obesity (continued). "Consistent with an increased proinflammatory activation profile of the DCs, we found that obesity altered the CD4+ Th cell pool in eWAT and liver, but not spleen, favoring Th1 cells at the expense of Th2 cells and Tregs in eWAT and increasing Th1 cells, Th17 cells, and Tregs in the liver." (PMID 37140993, 2023). "For example, ILC1 cells expand during obesity and promote tissue inflammation through inflammatory signaling, while ILC2 cells, which may function to suppress inflammation and promote Th2 phenotype of tissue-resident CD4+ cells, are depleted and inhibited." (PMID 35399946, 2022). "Leptin plays a role in T-cell thymus development, naive CD4+ T-cell proliferation, and Ki67 expression in CD4+ T cells, and HIV patients with higher leptin levels have better immune reconstitution, suggesting that obesity may play a protective role in immune reconstitution in HIV patients." (PMID 36584083, 2022). "Similarly, in mice, an accumulation of CD4+ Th cells and CD8+ cytotoxic T cells and reduction of FoxP3+ T regulatory (Treg) cells have also been observed in the small and large intestine in a diet-induced obesity (DIO) model." (PMID 35252310, 2022). "The study aimed to follow up on the changes in the peripheral CD4+ T lymphocytes and the pro-inflammatory cytokines; IL-6, TNF-alpha, MCP-1, and IL-10 at baseline and 12 weeks post-surgical intervention by the laparoscopic gastric sleeve (LGS) in morbidly obese patients (class III obesity subjects)." (PMID 33981153, 2021). "However, the mechanisms that may explain this contrast found in T cells from people with obesity (higher CD8+ cells in adipose tissue and higher CD4+ cells in peripheral blood) are still unclear." (PMID 34445165, 2021). "CD4+ T cells could be essentially involved as H2A−/− mice, which lack CD4+ T cells, did not develop an obesity memory and an accelerated weight regain occurred when CD4+ T cells of formerly obese mice were introduced to Rag1−/− mice." (PMID 32411095, 2020). "During obesity, the population of ATMs within the VAT increases up to 40–50% of the stromal vascular fraction, become metabolically activated, secrete pro-inflammatory cytokines, and engage in “inflammatory cross-talk” with other immune cells, notably CD4+ T cells." (PMID 32499756, 2020). "In the univariate analyses, the following variables were significantly associated with higher odds of having an ALF (p < 0.05): older age, unemployment, lower CD4+ cell count, obesity, not currently receiving ART, currently receiving HCV treatment, and high-risk alcohol consumption." (PMID 29857547, 2018). "This change in T cell populations during obesity contributes to the pro-inflammatory state of the adipose tissue: both CD8+ T cells and pro-inflammatory CD4+ Th1 cells express the pro-inflammatory cytokine IFN-γ, whereas effector CD4+ Th17 cells express the pro-inflammatory cytokine IL-17." (PMID 29868016, 2018). "However, adipose tissue changes in HIV should not be considered “equivalent” to obesity, as marked differences in CD4+ T cell and macrophage profiles are present in the two conditions." (PMID 30559739, 2018). "In this study, to test the hypothesis that obesity may contribute to the aging of human T-cell immunity, a thousand atomic-bomb survivors were examined for obesity status and ability to produce naive T cells, i.e., T-cell receptor excision circle (TREC) numbers in CD4 and CD8 T cells." (PMID 24651652, 2014). "Thus, it is postulated that senescent CD4 T-cells could potentially contribute to the negative effects of obesity." (PMID 38317257, 2024). "However, previous cardiac remodelling in end-stage HF patients may lead to a higher percentage of circulating CD4+ T cells which does not further increase in obesity." (PMID 37885885, 2023). "Thus, senescent CD4 T cells are suggested to be a negative legacy effect of obesity." (PMID 36685567, 2022).